SNORD116-10 (small nucleolar RNA, C/D box 116-10)
Synonyms: HBII-85-10
Gene: Small nucleolar RNA gene on chromosome 15 (25,074,114 to 25,074,215, forward strand). Ensembl gene ENSG00000200661.
Gene Ontology:
Biological process: RNA processing
Cellular component: nucleolus
Homologues: Orthologues: chimpanzee SNORD116 (96% identical), macaque SNORD116 (79% identical), guinea pig SNORD116 (65% identical), mouse Gm22373 (60% identical), rat LOC120100337 (55% identical), rabbit SNORD116 (48% identical). Paralogues in human: SNORD116-15 (77% identical), SNORD116-17 (77% identical), SNORD116-19 (77% identical), SNORD116-14 (76% identical), SNORD116-18 (76% identical), SNORD116-20 (76% identical), SNORD116-21 (76% identical), SNORD116-22 (76% identical), SNORD116-12 (75% identical), SNORD116-16 (75% identical), SNORD116-2 (73% identical), SNORD116-23 (73% identical), and 20 more.